CYP2E1 (cytochrome P450 family 2 subfamily E member 1)
Description:
A cytochrome P450 monooxygenase involved in the metabolism of fatty acids. Mechanistically, uses molecular oxygen inserting one oxygen atom into a substrate, and reducing the second into a water molecule, with two electrons provided by NADPH via cytochrome P450 reductase (NADPH--hemoprotein reductase). Catalyzes the hydroxylation of carbon-hydrogen bonds. Hydroxylates fatty acids specifically at the omega-1 position displaying the highest catalytic activity for saturated fatty acids. May be involved in the oxidative metabolism of xenobiotics (Probable).
Synonyms: CYP2E; CPE1; P450-J; P450C2E
Tractability: Small molecule: a structure with a bound ligand is known; it has a binding pocket of medium quality; it belongs to a druggable protein family. Antibody: UniProt places it where antibodies can reach, with medium confidence. PROTAC: ubiquitination databases record sites on it; its protein half-life has been measured; a small molecule that binds it is known.
Target class: Cytochrome P450; Cytochrome P450 family 2; Cytochrome P450 2E1; Cytochrome P450 family 2E; Enzyme
Safety:
Unwanted effects reported when the protein is acted on. In parentheses: how it was acted on, where the effect was seen, and who reports it.
alcoholism (source: ClinPGx)
hepatotoxicity (source: ClinPGx)
severe emesis (source: ClinPGx)
toxic liver disease (source: ClinPGx)
Gene: Protein-coding gene on chromosome 10 (133,520,406 to 133,561,220, forward strand). Ensembl gene ENSG00000130649.
Subcellular location: Endoplasmic reticulum membrane; Microsome membrane; Mitochondrion inner membrane
Subcellular location (Human Protein Atlas): Endoplasmic reticulum; Mitochondria
Pathways (Reactome):
Metabolism: Biosynthesis of maresin-like SPMs; CYP2E1 reactions; Xenobiotics
Drug ADME: Aspirin ADME; Paracetamol ADME
Gene Ontology:
Molecular function: 4-nitrophenol 2-monooxygenase activity; enzyme binding; heme binding; long-chain fatty acid omega-1 hydroxylase activity; monooxygenase activity; oxidoreductase activity; oxidoreductase activity, acting on paired donors, with incorporation or reduction of molecular oxygen, reduced flavin or flavoprotein as one donor, and incorporation of one atom of oxygen; arachidonate epoxygenase activity; Hsp70 protein binding; Hsp90 protein binding; oxidoreductase activity, acting on paired donors, with incorporation or reduction of molecular oxygen, NAD(P)H as one donor, and incorporation of one atom of oxygen; oxygen binding; fatty acid omega-1 hydroxylase activity; iron ion binding; oxidoreductase activity, acting on paired donors, with incorporation or reduction of molecular oxygen
Biological process: 4-nitrophenol metabolic process; lipid hydroxylation; long-chain fatty acid metabolic process; monoterpenoid metabolic process; steroid metabolic process; xenobiotic metabolic process; benzene metabolic process; carbon tetrachloride metabolic process; epoxygenase P450 pathway; halogenated hydrocarbon metabolic process; long-chain fatty acid biosynthetic process; fatty acid metabolic process
Cellular component: cytoplasm; endoplasmic reticulum membrane; mitochondrial inner membrane; endoplasmic reticulum
Genetic constraint (gnomAD): Loss-of-function variants: 31 observed, 45.8 expected, observed/expected ratio (o/e) 0.68, 90% interval 0.51 to 0.91. The upper end of that interval is the gene's LOEUF score, 0.91, which puts it in group 3 of 6, group 1 being the genes least tolerant of losing a copy. Missense variants: 565 observed, 664.41 expected, observed/expected ratio (o/e) 0.85, 90% interval 0.79 to 0.91. Synonymous variants: 244 observed, 261.87 expected, observed/expected ratio (o/e) 0.93, 90% interval 0.84 to 1.04.
Homologues: Orthologues: chimpanzee CYP2E1 (98% identical), macaque CYP2E1 (94% identical), guinea pig CYP2E1 (79% identical), rat Cyp2e1 (79% identical), rabbit CYP2E1 (79% identical), mouse Cyp2e1 (78% identical), dog CYP2E1 (77% identical), pig CYP2E1 (71% identical), macaque CYP2E1 (54% identical). Paralogues in human: CYP2C19 (57% identical), CYP2C9 (57% identical), CYP2C18 (57% identical), CYP2C8 (57% identical), CYP2F1 (47% identical), CYP2A13 (47% identical), CYP2A6 (46% identical), CYP2B6 (46% identical), CYP2A7 (45% identical), CYP2S1 (40% identical), CYP2J2 (40% identical), CYP2D6 (39% identical), and 3 more.
Diseases named in the same sentence as CYP2E1 in open-access papers:
CYP2E1 is named in the same sentence as 229 diseases in open-access papers, as found by Europe PMC text mining. Sharing a sentence is not in itself a finding about the gene and the disease. The quoted sentences say what the papers report.
Hepatic steatosis (67 papers, 2009 to 2025). Steatosis is a term used to denote lipid accumulation within hepatocytes. "CYP2E1 was found to be closely associated with the development of fatty liver disease, and liver steatosis due to alcohol intake was more severe in normal mice compared to CYP2E1 knockout mice." (PMID 37432394, 2023). "In ALD, an increased amount of reactive oxygen species (ROS) is produced from alcohol through Cyp2e1, causing hepatic steatosis and oxidative stress injury." (PMID 36432440, 2022). "On the other hand, CYP2E1-dependent ROS increase type I collagen synthesis and promote fibrosis, indicating that CYP2E1 was closely associated with hepatic steatosis and fibrosis." (PMID 36555703, 2022). "Consistent with this, CYP2E1 has been implicated in ROS generation and mitochondrial dysfunction in alcohol-induced hepatic steatosis." (PMID 32966340, 2020). "BBR treatment likely ameliorated hepatic steatosis and fibrosis by protecting the liver from injury caused by lipoperoxide, because the mRNA expression of CYP2E1 and CYP4A10 was downregulated, and the mRNA expression of catalase was upregulated by BBR." (PMID 26857750, 2016). "Hepatic CYP2E1 induction in obese patients would not only cause more frequent or more severe APAP hepatotoxicity but may also favor the transition of fatty liver to NASH." (PMID 36713231, 2023). "Cytochrome P4502E1 (CYP2E1) has been suggested to play critical roles in the pathogenesis of alcoholic fatty liver (AFL), but the underlying mechanisms remains unclear." (PMID 24892905, 2014). "High-fat diet-induced obese mice exhibited markedly elevated CYP2E1 expression and activity, which positively correlated with increased adiposity, hepatic steatosis, and mitochondrial dysfunction." (PMID 41420839, 2025). "The regulation of hepatic CYP2E1 and CYP4A expression involves several factors that have been associated with the pathogenesis of hepatic steatosis and NASH." (PMID 38836220, 2024). "Cyp2e1−/− mice expressing the human CYP2E1 transgene show increased hepatic steatosis, oxidative stress, insulin resistance, and liver injury." (PMID 40452921, 2024). "At first glance, it seems surprising, since CYP2E1 activity and expression were found to be elevated in human steatohepatitis and rodent alcohol and methionine-induced liver steatosis." (PMID 39061835, 2024). "Further, alcohol consumption under conditions of obesity worsens the severity of fatty liver disease through CYP2E1 activation in rodent models and in humans." (PMID 39058136, 2024). "In fatty liver disease, oxidative damage to the liver is thought to arise in part from CYP2E1-mediated oxidative stress, which is elevated with obesity and excess alcohol consumption." (PMID 39058136, 2024). "A low hesperidin dose showed an inhibitory effect against CYP2-E1 in fatty liver disease and in thioacetamide-induced hepatotoxicity." (PMID 38087036, 2024). "Our findings also suggest that CYP1A2 plays a more critical role than CYP2E1 in acute alcohol-induced fatty liver disease." (PMID 39120332, 2024). "Activating polymorphisms such as the c2 allele, which contains a cytosine-to-thymine and a guanine-to-cytosine transversion before the regulatory region of the CYP2E1 gene, have been shown to enhance the severity of fatty liver disease." (PMID 39058136, 2024). "It has been shown in cell cultures of human hepatocytes that the induction of CYP2E1 correlated significantly with the degree of hepatic steatosis." (PMID 37629519, 2023). "In keeping with the role of some fatty acids or lipids, a recent interventional study in healthy individuals showed that a short-term regular diet supplemented with whipped cream induced hepatic steatosis and significantly enhanced CYP2E1 activity." (PMID 36713231, 2023).
Hepatic steatosis (continued). "To clarify the molecular mechanism by which probiotics decreased the oxidative stress in VPA-treated mice, we first explored the level of CYP2E1, which has been demonstrated to promote ROS production and liver steatosis in VPA-treated mice." (PMID 37971986, 2023). "Histological and qPCR analyses revealed that CYP2E1 inhibition alleviated hepatic steatosis, inflammation, and fibrosis in USP14-overexpressing mice." (PMID 37633951, 2023). "Recently, increased CYP2E1 protein expression has been observed in fatty liver and non-alcoholic steatohepatitis (NASH) in both humans and rodents." (PMID 36555703, 2022). "Our results support the likelihood of hepatic steatosis development (CYP2E1) and impaired fatty acid oxidation (CYP4A)." (PMID 33926097, 2021). "Our data suggest that HFD induced the overexpression of both mRNA and protein levels of CYP2E1 in hepatic steatosis, while SEM significantly reverted the transcription of cyp2e1, thus reducing the oxidative stress." (PMID 34960036, 2021). "Elevated intestinal and hepatic CYP2E1 are important for promoting alcohol-induced gut leakiness and hepatic steatosis, respectively, possibly via oxidative/nitrative stress and the apoptosis of parenchymal cells." (PMID 34573017, 2021). "For example, enhanced enzymatic activity of CYP2E1 promoted reactive oxidative stress (ROS) production, resulting in oxidative stress and hepatic steatosis in mice and LO2 cells." (PMID 34461916, 2021). "Until now, research on the effects of tea on the regulation of CYPs mainly focuses on CYP2E1, while our study indicates the cyp2c subfamily as a promising target for matcha green tea to improve steatosis hepatitis." (PMID 34204055, 2021). "According to recent studies, and in agreement with our findings on ovariectomized rats, the development of hepatic steatosis correlates with upregulation of CYP2E1." (PMID 33926097, 2021). "Numerous studies have demonstrated that oxidative stress indicated by the elevated levels of CYP2E1, iNOS, and nitrated proteins plays a key role in promoting alcohol-mediated intestinal barrier dysfunction and fatty liver disease through the gut–liver axis." (PMID 34573017, 2021). "In rodent models, treatment with antioxidants or a specific inhibitor of CYP2E1 significantly prevented binge alcohol-mediated leaky gut and fatty liver disease, while Cyp2e1-knockout mice were also quite resistant to these changes." (PMID 33806556, 2021). "Microsomal Cyp2e1 is a major site of fatty acid metabolism, which has been found to be elevated in fatty liver diseases in humans and rodents." (PMID 32937969, 2020). "CYP2E1 was reported as a major contributor to ROS generation and played a pivotal role in ethanol-induced fatty liver and oxidative stress." (PMID 31583074, 2019). "We found that the C3 activation products C3a and Asp play key roles in the development of hepatic steatosis by regulating the expression of Gly-tRF via CYP2E1." (PMID 31076642, 2019). "The development of hepatic steatosis was accompanied by the rise of lipid peroxidation and higher cytochrome P450 2E1 (Cyp2e1) gene expression in HF mice compared with the control group." (PMID 31505802, 2019). "Both C3a and Asp promote the expression of Gly-tRFs via mediating the expression of CYP2E1, which contributes to the development of liver steatosis by regulating Sirt1 expression." (PMID 31076642, 2019). "The inhibition of CYP2E1 activity has been shown to result in successful recovery of ethanol-induced fatty liver." (PMID 31906014, 2019). "The expression and activity of CYP2E1 are upregulated due to alcohol exposure, which leads to liver injury and the suppression of CYP2E1 activity reduces the incidence of ethanol-induced fatty liver." (PMID 30200508, 2018). "To shed a light on potential metabolic reasons of increased body weight gain and hepatic steatosis in WT-FF than Cyp2e1-null-FF, we performed indirect calorimetry study on both mouse groups fed FF." (PMID 28051126, 2017).
Hepatic steatosis (continued). "CYP2E1 activity has been shown to correlate with alcohol-induced liver injury, and inhibition of CYP2E1 prevented the induction of hepatic steatosis and ROS production in models of alcoholic steatohepatitis." (PMID 26497211, 2015). "In micropigs fed alcohol orally, liver steatosis and apoptosis were shown to be accompanied by increased mRNA levels of CYP2E1 and selective ER stress markers." (PMID 24868470, 2014). "For instance, in a study with CIAI rats to examine effects of selective inhibition of CYP2E1 on the development of alcoholic fatty liver, liver triglycerides were lower." (PMID 24868470, 2014). "In summary, the current study demonstrated that CYP2E1 suppression by CMZ completely blocked chronic ethanol-induced fatty liver in mice treated with Lieber-DeCarli liquid diet (containing 5% ethanol)." (PMID 24892905, 2014). "In this study, we evaluated the protective effects of CMZ, a specific CYP2E1 inhibitor, on chronic ethanol-induced fatty liver." (PMID 24892905, 2014). "CYP2E1 overexpression in a transgenic mouse model induced hepatic steatosis and injury, whereas application of CYP2E1 antibody inhibited hepatic lipid peroxidation in murine NASH model." (PMID 24379011, 2013). "Increased oxidative stress from induction of CYP2E1 in vivo sensitizes hepatocytes to LPS and TNFα toxicity and CYP2E1 knock-in mice showed elevated hepatic steatosis and liver injury after alcohol feeding." (PMID 22500241, 2012). "Increased CYP2E1 protein levels are observed in animal models of fatty liver diseases and in morbid obese men with NAFLD and patients with NASH." (PMID 20300478, 2009). "Additionally, the rate-limiting enzyme in IS formation, CYP2E1, is upregulated in liver steatosis and circulating IS levels increase with rising triacylglycerolemia." (PMID 41305664, 2025). "In mice with fatty liver disease, AL attenuates the oxidative stress and inflammation by reducing fat accumulation, liver enzymes and the expression of microsomal protein cytochrome P450 2E1 (CYP2E1)." (PMID 39827123, 2025). "Ethanol-induced suppression of Akt phosphorylation and pharmacological modulation of Akt can result in CYP2E1-induced hepatic oxidative stress, which could be a viable treatment for ethanol-induced fatty liver." (PMID 37047003, 2023). "Other mechanisms of CYP2E1-mediated hepatic steatosis may include an impairment of protein kinase B activity by CYP2E1—mediated oxidative stress —and a suppression of PPAR a by oxidative stress." (PMID 37629519, 2023). "CYP2E1 knock-in mice had increased hepatic steatosis and liver damage after alcohol intake." (PMID 34567217, 2021). "This increase has been linked with an increased expression of isoform 2E1 of cytochrome P450 (CYP), as valproic acid-induced ROS accumulation and hepatic steatosis were attenuated when CYP2E1 was inhibited using the CYP2E1 inhibitor or CYP2E1 CRISPR knockdown (CYP2E1-KD)." (PMID 35052590, 2021). "To verify if SEM may protect mice from hepatic steatosis through its antioxidant activity, we analyzed the expression of the enzymes CYP2E1 and NOX2 as well as of the uncoupling protein UCP2, which are all importantly involved in oxidative stress generation." (PMID 34960036, 2021). "In addition, hepatic lipid dysregulation reflects changes in the cytochrome P450 enzyme family, including CYP2E1, and contributes to hepatic steatosis development." (PMID 33926097, 2021). "In addition, adeno-associated virus 9 (AAV9)-shRNAs or CMZ, an inhibitor of CYP2E1, was used to downregulate Cyp2e1, and the effect on liver steatosis was evaluated." (PMID 31076642, 2019). "We aimed to address: 1) whether CYP2E1 inhibition by CMZ could suppress chronic ethanol-induced fatty liver?" (PMID 24892905, 2014). "Administration of FZHY could reduce hepatic expression of CYP2E1 and HO-1, which was concomitant with ameliorated hepatic steatosis, inflammation and fibrosis induced by MCD-treatment." (PMID 22452814, 2012).